BCL6 (BCL6 transcription repressor)
Diseases named in the same sentence as BCL6 in open-access papers (continued):
Sharing a sentence is not in itself a finding about the gene and the disease.
B-cell lymphoma (continued). "This study investigated the epidemiological and clinical peculiarities of BCL2 and BCL6 rearrangement in patients with high grade B-cell lymphoma (HGBL) from Taiwan, compared with data from Western countries." (PMID 33807449, 2021). "MYC/BCL2/BCL6 triple-hit lymphoma (THL) is an uncommon subset of high-grade B-cell lymphoma with aggressive clinical behavior and poor prognosis." (PMID 34113336, 2021). "In particular, the downregulated genes were enriched of transcripts decreased in post-GC BCL6 dependent B cell lymphomas and present in the GCB DLBCL signature." (PMID 32341372, 2020). "Inhibition of HSPH1 downregulates the expression of Bcl-6 and c-Myc and hampers the growth of human aggressive B cell non-Hodgkin lymphoma." (PMID 33042807, 2020). "The incidence of BCL6 translocation in our study supported the evidence that BCL6 gene translocation in B-Cell NHL constituted about 30-40% of all DLBCL 44,45." (PMID 31892985, 2020). "B-cell CLL/lymphoma 6 (BCL6) is a highly conserved zinc finger transcriptional factor and is implicated in the pathogenesis of human B-cell lymphomas by controlling the transcription of oncogenes." (PMID 33282727, 2020). "Between 15 and 20 months of age, 36–62% of BCL6-overexpressing mice had developed B-cell lymphoma (compared to 2–8% in wild-type mice), and 75% of these cases resembled DLBCL." (PMID 33277464, 2020). "BCL6 translocation and clinical features of B-cell NHL particularly DLBCL has been the subject of controversy." (PMID 31892985, 2020). "Restoration of BCL6 function in the B cell lymphoma cell lines has been shown to inhibit B-cell lymphogensis, indicating a potential critical role played by FBXO11 in the modulation of B cell survival." (PMID 32117459, 2020). "FBXO11 is known to play a critical role in maintenance of B cell levels via the BCL6 pathway and FBXO11 loss of function is frequently observed in B cell lymphoma cell lines and increased B-cell levels, as we observed in the Fbxo11tmb2/+ knockout mouse." (PMID 32117459, 2020). "Translocations (e.g., MYC, BCL2, and BCL6) are quite common in B-cell lymphomas and NHLs in general." (PMID 33277464, 2020). "The transcription factor BCL6, a protein that normally suppresses the DNA damage response during immune cell maturation, and a known driver of B-cell lymphoma, was shown to mediate the survival of glioblastoma cells." (PMID 32320427, 2020). "The molecular function of BCL6 and its role in cancer has mainly been described in B-cell lymphomas, but the importance of BCL6 as an oncogene also in other malignancies is currently gaining more attention." (PMID 32234966, 2020). "FBXO11, through regulation of BCL6, modulates B-cell survival and plays a crucial role in B-cell lymphoma." (PMID 32117459, 2020). "Multiple genetic aberrations in the regulation of BCL6, including in acetyltransferase genes, occur in clinically aggressive B-cell lymphomas and lead to higher expression levels and activity of this transcriptional repressor." (PMID 31712669, 2019). "A chromosomal translocation mutation implicated in B-cell lymphoma was linked to the GAS5 lncRNA; the mutation causes fusion of the GAS5 transcript to the BCL6 gene." (PMID 31379598, 2019). "This provides strong support for the importance of BCL6 in B-cell lymphoma, but many details remain to be defined." (PMID 31788471, 2019). "The activity of BCL6 can be deregulated by a variety of mechanisms and contributes to the development of B-cell lymphoma." (PMID 31788471, 2019). "Together, these findings all provide the basis for directly targeting BCL6 as therapeutic approach for B cell lymphoma, but these approaches are yet to be tested in the clinic." (PMID 31788471, 2019). "We are only beginning to scratch the surface of the complex epigenetic basis for B-cell lymphoma, and the role that BCL6 plays in this setting." (PMID 31788471, 2019). "BCL6 overexpression inhibits ROS generation and apoptosis induced by chemotherapy in B-cell lymphoma cells." (PMID 30805081, 2019).
B-cell lymphoma (continued). "Inhibitors of HSP90 have been shown to be effective in inducing apoptosis of B cell lymphomas that have a GC origin and overexpress B cell lymphoma-6 (BCL6) protein." (PMID 31042473, 2019). "The BCL6 gene has long been recognized as an important oncogene in B-cell lymphoma due to its direct deregulation by promiscuous translocations that place it under control of the immunoglobulin heavy-chain locus or a variety of alternative regulatory elements." (PMID 31788471, 2019). "We selected primers targeting the sequences of BCL6 intron 1 and the IGH switch region, because BCL6/IGH translocations frequently occur at these regions in B-cell lymphomas." (PMID 30323893, 2018). "BCL6 was a critical prooncogene of human B-cell lymphomas which promoted tumor progress and contributed to malignant behavior in several kinds of cancers." (PMID 30420967, 2018). "HDACis treatment demonstrated favorable results in B-cell lymphomas where the pathogenesis is secondary to the deregulation of the BCL6 proto-oncogene." (PMID 30096875, 2018). "Induction of these shared LTR elements is likely to be induced by the same transcriptional regulators induced in activated B cells (e.g., NF-κB) or germinal center B cells (e.g., BCL6), which are also overexpressed in B cell lymphomas." (PMID 29312197, 2017). "A positive correlation between Bcl-6 and cyclin A or cyclin B1 expression has previously been reported for B-cell lymphomas where Bcl-6 promotes cell proliferation." (PMID 27880939, 2017). "For example, in some B-cell lymphomas, Bcl6 expression was inversely correlated with LMP1 expression, and some data suggested that LMP1 can cause downregulation of Bcl6." (PMID 28738086, 2017). "Among many other sites, BRD4 has been shown to bind superenhancers of the POUF2AF1 and BCL6 genes in B cell lymphoma lines." (PMID 28588024, 2017). "A recent study for the first time has demonstrated that LITAF, a novel target of BCL6, regulates autophagy in mature B-cell lymphomas." (PMID 27764808, 2016). "On the contrary, we characterized LITAF as a transcription factor in B-cell lymphoma, translocating to the nucleus and repressing BCL6 mRNA expression by binding to its regulatory region." (PMID 27764808, 2016). "In the literature B-cell lymphomas with concurrent MYC/BCL2 or MYC/BCL6 rearrangements are grouped together as double-hit B-cell lymphomas." (PMID 26573234, 2016). "Of note, we show that BCL6, a crucial player involved in B cell-lymphoma, is increased in MCF-7 cells upon direct co-incubation with ASCs promoting proliferation and upon indirect co-culture in a transwell system with ASCs facilitating EMT in MCF-7 cells." (PMID 26439686, 2015). "Biopsy was performed from skin lesion which was reported as CD20+, BCL2+, MUM1+, BCL6+ high grade B cell lymphoma infiltration." (PMID 26457084, 2015). "BCL6 is a transcriptional repressor which frequently disrupted by translocations in B-cell lymphomas." (PMID 26308950, 2015). "BCL6, an important player in B-cell lymphoma and breast cancer progression, is crucial for this transition." (PMID 26439686, 2015). "For instance, in contrast to its positive role in CD19+ B lymphocytes, STAT5 has been shown to repress BCL6 in B cell lymphoma." (PMID 23852366, 2013). "To further characterize the subtype of the B cell lymphoma in study, we used antibodies against subtype markers, Bcl-6, CD10 and IRF4 for immunohistochemistries." (PMID 22848504, 2012). "Distinction between different types of B-cell lymphoma, pseudo-B-cell lymphoma, and secondary cutaneous B-cell lymphoma is made using Bcl-2, Bcl-6, CD10, MUM-1, and FOXP1." (PMID 29147306, 2012). "rs1056932 in BCL6 was previously found to be associated with NHL, B-cell lymphomas and T-cell lymphomas." (PMID 22347493, 2012).
B-cell lymphoma (continued). "For example, the BCL6 and PLZF proteins are causally involved in several types of B-cell lymphomas and acute promyelocytic leukaemia." (PMID 21702992, 2011). "However, a similarly paradoxical finding of increased BCL6 expression and increased intronic hypermethylation was observed in human B cell lymphoma cells (Raji), which express high levels of BCL6 compared to plasmacytoma cells (H929)." (PMID 40949964, 2025). "Beyond B cell lymphomas, BCL6 inhibition also impacts Tfh cells and GC B cells and may regulate immune responses during infectious disease, auto-immunity, or allo-immune responses." (PMID 41246349, 2025). "Furthermore, BCL6 inhibitors are currently in clinical trials for treatment of B-cell Non-Hodgkin’s Lymphoma, streamlining the process for regulatory approval as a new potential T1D immunotherapy." (PMID 40909612, 2025). "Furthermore, cytogenetic profiling is crucial in identifying MYC, BCL2, and BCL6 rearrangements in high-grade B-cell lymphomas (HGBL-MYC/BCL2/BCL6), which define cases with aggressive clinical behavior and poor prognosis." (PMID 40150070, 2025). "Recurrent gene fusions and chromosomal rearrangements involving MYC, BCL2, and BCL6 are hallmark genetic events in DLBCL and are defining features of specific DLBCL subtypes and high-grade B-cell lymphomas (HGBCL), as per the World Health Organization (WHO) 2016 and 2022 classifications." (PMID 41010038, 2025). "Large B-cell lymphomas with a MYC rearrangement, along with B-cell lymphoma 2 (BCL2) and/or B-cell lymphoma 6 (BCL6) rearrangements, are being classified as high-grade B-cell lymphomas (HGBLs) and are frequently referred to as double-hit (DHL) and triple-hit lymphomas (THL), respectively." (PMID 38397877, 2024). "Given the characteristics of mildly elevated cerebrospinal fluid protein levels, lymph node histopathology, Myc and BCL-6 rearrangement detected by standard cytogenetics, and weak Bcl-2 positivity, the disease is consistent with a diagnosis of high-grade B-cell lymphoma." (PMID 39969355, 2024). "To date, a number of biomarkers with a diagnostic value for each B-cell lymphoma subtype have been determined: BCL2, BCL6, CD10, CD21, and STMN1 in FL; D1 and SOX11 in MCL; FOXP1 and MUM1 in ABC-DLBCL; CD10, BCL2, BCL6, LMO2, and GCET1 in GC-DLBCL; and CD30, CD15, EBV, BOB1, OCT2, and CD79a in HL." (PMID 37894763, 2023). "Bcl6 is a well-studied oncogene protein known for its significance in B cell lymphoma." (PMID 37967194, 2023). "BCL6 (B cell lymphoma 6) was an oncogene in B cell lymphoma." (PMID 36945884, 2023). "BCL6 is also an oncogenic driver for B-cell lymphoma and follicular lymphoma." (PMID 37187757, 2023). "Double-hit and triple-hit B-cell lymphomas are generally associated with poor prognosis although a more favorable outcome has been reported for a patient with MBNL1::BCL6 in whom absence of BCL6 overexpression was also noted." (PMID 37371852, 2023). "DLBCLs often express BCL6 and BCL6 is frequently misregulated in B-cell lymphomas." (PMID 35982974, 2022). "The BCL6 gene was discovered as an oncogene involved in the growth and development of B-cell lymphoma, which could contribute to the malignant phenotype by inhibiting DNA damage repair and blocking B-cell terminal differentiation." (PMID 36076940, 2022). "BCL6 has been primarily studied as a mediator of tumor progression in B‐cell lymphoma." (PMID 33932086, 2021).
B-cell lymphoma (continued). "Since the discovery of chromosomal translocations of ZBTB16 in human acute promyelocytic leukemia and BCL6 in B-cell lymphomas in the 1990s, numerous studies have been performed to investigate roles of ZBTB proteins in the development, function and neoplastic transformation of hematopoietic cells." (PMID 34349770, 2021). "In the new WHO classification, the high-grade B-cell lymphoma has been redefined, including in this subgroup the entities carrying MYC rearrangement (MYC-R) associated to BCL2 rearrangement (BCL2-R) and/or BCL6 rearrangement (BCL6-R) named as double- and triple-hit lymphomas." (PMID 33768318, 2021). "The 2016 revised World Health Organization guidelines of lymphoid neoplasms classified large B-cell lymphoma with rearrangements of MYC and BCL2 or/and BCL6 in a distinct category to be designated high-grade B-cell lymphoma, also called double-hit lymphoma (DHL) or THL." (PMID 34113336, 2021). "High-grade B cell lymphomas with rearrangements on C-MYC and BCL2 and/or BCL6 (HGBL with MYC and BCL2 and/or Bcl6 rearrangement) are associated with worse clinical outcomes and thus were introduced as a separate new category in the recently updated WHO classification." (PMID 32613279, 2020). "Importantly, all of these inhibitors act by blocking the interaction between BCL6 and its co-repressors, resulting in re-expression of BCL6 target genes, proliferation arrest and apoptosis in B-cell lymphoma xenografts." (PMID 32234966, 2020). "TOX was also expressed in reactive GC B cells and in primary cutaneous B-cell lymphomas (BCL6+ primary cutaneous large B-cell lymphoma leg-type and secondary cutaneous DLBCL), indicating that this gene may play a role in B-cell lymphoma pathogenesis." (PMID 32106280, 2020). "In addition, it was shown using ex vivo screening that BCL6 inhibitors were active in killing primary human B-cell lymphoma cells (58, –60)." (PMID 32234966, 2020). "Finally, we found a significant downregulation BCL6 (1.5-fold, p = 0.001) in SUDHL5, in agreement with a very recent study demonstrating romidepsin-mediated depletion of BCL6 in B-cell lymphoma cells." (PMID 32264925, 2020). "C-MYC, BCL2 and BCL6 genes are the most commonly oncogenes involved in B-Cell lymphomas." (PMID 31892985, 2020). "Here, we will review the role of genetic alterations in altering BCL6 function in B-cell lymphoma." (PMID 31788471, 2019). "Indeed, high-grade B-cell lymphomas with chromosomal breakpoints affecting the MYC locus in combination with breakpoints involving the BCL2 or BCL6 genes, constitute a separate entity frequently called “DH lymphomas”1." (PMID 30926794, 2019). "Characterizing these roles, as well as the complex interplay of epigenetic crosstalk and BCL6 function, will be critical in our understanding of the etiology of B-cell lymphoma and may highlight novel avenues for targeting this critical axis." (PMID 31788471, 2019). "B-cell lymphoma 6 (BCL6) is initially discovered as an oncogene in B-cell lymphomas." (PMID 30805081, 2019). "The data presented here reveal that AIP is a positive regulator of BCL6 protein expression, which is commonly upregulated in B cell lymphomas, and show that AIP binds to an E3 ligase (FBXO11) and a DUB (UCHL1), both of which have been associated with DLBCL pathobiology." (PMID 31042473, 2019). "Here we review the direct and indirect mechanisms BCL6 dysregulation in B cell lymphoma, including transcriptional and post-translational regulation of BCL6 expression and activity, and the perturbation of BCL6-regulated epigenetic programs by cooperating chromatin modifying gene mutations." (PMID 31788471, 2019). "BCL6 is also important as a prognostic marker in high grade B-cell lymphoma." (PMID 28929458, 2018). "Thus, in contrast to human B-cell lymphomas, canine B-cell lymphomas have been shown to rarely express BCL6 and MUM1/IRF425." (PMID 29674676, 2018).
B-cell lymphoma (continued). "For the mouse-centric counterpart, u(MB, HB), BCL6 and GATA4 were central genes, associated with B-cell lymphoma and atrioventricular diseases respectively; GATA4 has also recently been linked to stress response and age-related inflammation in multiple tissues including the brain." (PMID 29161290, 2017). "Additionally, GFI1B was decreased in human BCL6-positive T- and B-cell lymphomas, analyzed by immunohistochemistry." (PMID 28401061, 2017). "However, in the post-rituximab era, there is controversy about the prognostic value of BCL6 expression in B-cell lymphomas." (PMID 28881619, 2017). "Additionally, a recent study has shown that miR-10a directly targets Bcl-6 to downregulate protein expression level in a murine B cell lymphoma cell line." (PMID 27815824, 2016). "Thus, most B cell lymphomas arise from GC B cells need continued expression of BCL6 to maintain their survival." (PMID 27815824, 2016). "CD20+, BCL2+, MUM1+, BCL6+ high grade B cell lymphoma infiltration was detected with skin biopsy." (PMID 26457084, 2015). "LITAF has been identified as a BCL6 target in mature B-cell lymphomas where it regulates autophagy." (PMID 26599546, 2015). "The human proto-oncogene BCL-6 on chromosome 3 at q27 encodes a BTB/POZ-zinc finger transcriptional repressor that is necessary for germinal center formation and is implicated in the pathogenesis of B cell lymphoma." (PMID 25477702, 2014). "Altered lipid metabolism has been associated with B-cell lymphoma, although not directly linked to Bcl6 so far." (PMID 24892698, 2014). "The human proto-oncogene BCL6 has been identified from chromosomal breakpoints in B-cell lymphomas." (PMID 25008234, 2014). "Pathologically elevated levels of BCL-6 have been reported for B-cell lymphoma cells." (PMID 24146931, 2013). "For example, in some cases like B-cell lymphomas, direct acetylation of p300 could hamper the oncogene BCL6 by disrupting HDAC activity." (PMID 24275784, 2012). "To test off-target activity of AID versus K3, we analysed mutations within the intronic region of Bcl6, which is known to be subjected to SHM in germinal centre B cells and germinal centre derived B cell lymphoma and which was shown to accumulate AID dependent mutations also in mice." (PMID 22363466, 2012). "For example, research shows that exosomes isolated from plasma of B-cell lymphoma patients carry mRNA of oncogenes (cMYC, BCL-6, BCL-XL), the tumor suppressors PTEN, and important signaling pathway molecules (NF-kβ, AKT) dysregulated in NHL, which may serve as prognostic markers of lymphomagenesis." (PMID 40646161, 2025). "Consequently, BCL6 has become an attractive therapeutic target for B-cell lymphomas and leukemias." (PMID 38397429, 2024). "Moreover, FBW7 reversely correlated with BCL6 in human B-cell lymphoma." (PMID 38485719, 2024). "Taken together, SC-1 carries three major rearrangements resulting in the gene fusions IGH::BCL2, IGH::MYC, and MBNL1::BCL6 which were characterized cytogenetically, genomically, and at the transcript level, thus, representing an exceptionally well characterized triple-hit B-cell lymphoma cell line." (PMID 37371852, 2023). "Interestingly, previous reports suggest a potential cooperativity between BCL6 and chromatin-modifying proteins such as EZH2, LSD1, and the NCOR/HDAC3 complex, suggesting that BCL6 may act as an epigenetic re-programming TF in cancers such as B-cell lymphoma." (PMID 35711675, 2022). "Furthermore, a small proportion of BCL6 transgenic mice can also develop T and B cell lymphoma." (PMID 25485281, 2014). "Furthermore, B-cell lymphoma cells are reportedly characterized by high levels of class I as well as class II HDACs which may interfere with BCL‐6 aggregate formation as we have observed upon co-expression of various HDAC members." (PMID 24146931, 2013).